TRPM3 (transient receptor potential cation channel subfamily M member 3)
Description:
Constitutively active, non-selective divalent cation-conducting channel that is permeable to Ca(2+), Mn(2+), and Mg(2+), with a high permeability for Ca(2+). However, can be enhanced by increasing temperature and by ligands, including the endogenous neurosteroid pregnenolone sulfate and sphingosine-1 and suppressed by intracellular Mg(2+). Implicated in a variety of cellular processes, including insulin/peptide secretion, vascular constriction and dilation, noxious heat sensing, inflammatory and spontaneous pain sensitivity. In neurons of the dorsal root ganglia, functions as thermosensitive channel for the detection of noxious heat and spontaneous pain. Suggested to function as an ionotropic steroid receptor in beta-cell, indeed pregnenolone sulfate leads to Ca(2+) influx and enhanced insulin secretion. Mediates Zn(2+) uptake into the lumen of pancreatic beta cell secretory granules, thereby regulating insulin secretion (By similarity). Forms heteromultimeric ion channels with TRPM1 which are permeable for Ca(2+) and Zn(2+) ions. Exists as multiple splice variants which differ significantly in their biophysical properties (By similarity).
Synonyms: LTrpC3; MLSN2; KIAA1616; GON-2; CTRCT50; NEDFSS
Tractability: Small molecule: it belongs to a druggable protein family. Antibody: UniProt places it where antibodies can reach, with high confidence; its Gene Ontology location is reachable by antibodies, with high confidence; UniProt predicts a signal peptide or a membrane-spanning region. PROTAC: its protein half-life has been measured.
Target class: Voltage-gated ion channel; Ion channel; Transient receptor potential channel
Gene: Protein-coding gene on chromosome 9 (70,529,060 to 71,446,977, reverse strand). Ensembl gene ENSG00000083067.
Subcellular location: Cell membrane
Subcellular location (Human Protein Atlas): Vesicles
Pathways (Reactome):
Transport of small molecules: TRP channels
Gene Ontology:
Molecular function: calcium channel activity; monoatomic cation channel activity; G-protein beta/gamma-subunit complex binding; phosphatidylinositol-4,5-bisphosphate binding; monoatomic ion channel activity
Biological process: calcium ion transmembrane transport; monoatomic cation transport; calcium ion transport; monoatomic cation transmembrane transport; protein homotetramerization; zinc ion transmembrane transport; monoatomic ion transport; protein tetramerization; transmembrane transport
Cellular component: plasma membrane; membrane
Genetic constraint (gnomAD): Loss-of-function variants: 71 observed, 180.29 expected, observed/expected ratio (o/e) 0.39, 90% interval 0.32 to 0.48. The upper end of that interval is the gene's LOEUF score, 0.48, which puts it in group 2 of 6, group 1 being the genes least tolerant of losing a copy. Missense variants: 1,745 observed, 2,242.9 expected, observed/expected ratio (o/e) 0.78, 90% interval 0.75 to 0.81. Synonymous variants: 741 observed, 819.85 expected, observed/expected ratio (o/e) 0.9, 90% interval 0.85 to 0.96.
Gene-disease validity (ClinGen):
ClinGen rates the evidence that TRPM3 causes each of these diseases.
syndromic complex neurodevelopmental disorder (autosomal dominant): Definitive. A disorder that involves more than one phenotype associated with the central nervous system, including but not limited to intellectual disability, autism, and seizures (epilepsy), and also a distinctive pattern of other features including dysmorphisms and/or congenital malformations.
cataract 50 with or without glaucoma (autosomal dominant): Moderate.
Homologues: Orthologues: macaque TRPM3 (99% identical), rat Trpm3 (98% identical), mouse Trpm3 (97% identical), chimpanzee TRPM3 (96% identical), dog TRPM3 (95% identical), pig TRPM3 (95% identical), rabbit TRPM3 (94% identical), guinea pig TRPM3 (94% identical), tropical clawed frog trpm3 (83% identical), zebrafish trpm3 (77% identical), Drosophila melanogaster Trpm (38% identical), Caenorhabditis elegans gon-2 (34% identical), and 4 more. Paralogues in human: TRPM1 (58% identical), TRPM7 (46% identical), TRPM6 (43% identical), TRPM2 (23% identical), TRPM4 (21% identical), TRPM5 (19% identical), TRPM8 (18% identical).
Diseases named in the same sentence as TRPM3 in open-access papers:
TRPM3 is named in the same sentence as 120 diseases in open-access papers, as found by Europe PMC text mining. Sharing a sentence is not in itself a finding about the gene and the disease. The quoted sentences say what the papers report.
chronic fatigue syndrome (15 papers, 2016 to 2025). "A recent analysis of gain-of-function mutations of TRPM3 revealed a role of this ion channel in chronic fatigue syndrome/myalgic encephalomyelitis and in the development of neuronal disorders." (PMID 38893478, 2024). "Reduction of TRPM3 (MIM 608961) is described to be associated with chronic fatigue syndrome/Myalgic encephalomyelitis patients, and FGF2 (MIM 134920) has been proposed to play a role in intussusceptive angiogenesis during COVID-19." (PMID 34452458, 2021). "Single nucleotide polymorphisms in the TRPM3 gene are enriched in individuals with systemic sclerosis, aspirin-exacerbated respiratory disease, and myalgic encephalomyelitis/chronic fatigue syndrome." (PMID 30883612, 2019). "Multiple single nucleotide polymorphisms have been reported in TRPM3 genes from isolated peripheral blood mononuclear cells, NK and B cells in Chronic fatigue syndrome/Myalgic encephalomyelitis (CFS/ME) patients and have been proposed to correlate with illness presentation." (PMID 27245705, 2016). "TRPM3 channels have been described as a molecular marker of chronic fatigue syndrome/myalgic encephalomyelitis." (PMID 40305282, 2025). "TRPM3 channels have been proposed as molecular markers for chronic fatigue syndrome/myalgic encephalomyelitis." (PMID 40871473, 2025). "This will facilitate genetic analysis of membrane proteins known as transient receptor potential melastatin 3 (TRPM3) ion channels in myalgic encephalomyelitis/chronic fatigue syndrome (ME/CFS) research." (PMID 36213251, 2022). "Furthermore, TRPM3 has been identified as a molecular marker for chronic fatigue syndrome/myalgic encephalomyelitis." (PMID 40305282, 2025). "TRPM3 activity is impaired in chronic fatigue syndrome/myalgic encephalomyelitis patients suggesting changes in intracellular Ca2+ concentration, which may impact natural killer cellular functions." (PMID 38123150, 2023). "Myalgic encephalomyelitis/chronic fatigue syndrome (ME/CFS) is a severe multisystemic condition associated with post-infectious onset, impaired natural killer (NK) cell cytotoxicity and impaired ion channel function, namely Transient Receptor Potential Melastatin 3 (TRPM3)." (PMID 35986236, 2022).
Intellectual disability (13 papers, 2019 to 2025). "De novo substitutions in TRPM3 gene were found to be associated with epilepsy, intellectual disability and developmental delay affecting motor and language skills." (PMID 39636905, 2024). "TRPM3 has been related to neurodevelopmental disorders concerning speech/language skills and mild-to-severe intellectual disability, while the LRP1B gene was found to be a major risk factor in the progression to Parkinson’s disease dementia." (PMID 38791296, 2024). "Gain-of-function mutations in TRPM3 have recently been shown to cause intellectual disability and seizures." (PMID 36181791, 2022). "The heterozygous missense variant in TRPM3, with links to ocular development and intellectual disability, is also notable, but it was inherited from the unaffected father." (PMID 35885948, 2022). "It was recently shown that mutations in TRPM3 are associated with developmental and epileptic encephalopathies manifesting as intellectual disability and seizures in children." (PMID 36181791, 2022). "Several studies have described that patients with TRPM3-mutations can have distinct morphological features and suffer from symptoms such as intellectual disability, speech retardation, epileptic seizures or heat insensitivity." (PMID 34948452, 2021). "It is interesting to note that almost all of the neuropathologies that were linked to the TRPM3 gene resulted in a state of intellectual disability in the affected patients." (PMID 33732703, 2021). "People with these diseases usually have both epilepsy and intellectual disabilities, and in some patients these conditions are associated with two mutations that change a gene called TRPM3." (PMID 32343227, 2020). "TRPM3 mutations in humans were recently reported to be associated with intellectual disability and epilepsy; the functional effects of those mutations, however, were not reported." (PMID 32343227, 2020). "A recent paper showed that two missense mutations in TRPM3 are associated with a neurodevelopmental disorder with intellectual disability, hypotonia and epilepsy, pointing to important roles of this channel in the human brain." (PMID 32343227, 2020). "Recently, two de novo substitutions in TRPM3 (V990M and P1090Q) were identified as the cause of intellectual disability and epilepsy in eight probands with developmental and epileptic encephalopathy (DEE)." (PMID 32427099, 2020). "Finally, several studies have recently described that patients with TRPM3-mutations can have distinct morphological features and suffer from symptoms such as intellectual disability, speech retardation, epileptic seizures or heat insensitivity." (PMID 34948452, 2021). "We conclude that de novo variants in TRPM3 are a cause of intellectual disability and epilepsy." (PMID 31278393, 2019).
epilepsy (12 papers, 2019 to 2026). A brain disorder characterized by episodes of abnormally increased neuronal discharge resulting in transient episodes of sensory or motor neurological dysfunction, or psychic dysfunction. "Patients with DEE-associated TRPM3 mutations exhibit a spectrum of neurological and developmental symptoms, including global developmental delay, epilepsy, altered pain perception, and cerebellar abnormalities such as ataxia and hypotonia." (PMID 40806522, 2025). "TRPM3 gain-of-function mutations were associated with cognitive deficits and epilepsy." (PMID 40537608, 2025). "Like patients harboring the recurrent p.Val1002Met TRPM3 variant, patients with the novel variants presented with a neurodevelopmental disorder of variable severity, variably associated with skeletal abnormalities and epilepsy." (PMID 36648066, 2023). "We propose that de novo substitutions of TRPM3 are a cause of ID and epilepsy." (PMID 31278393, 2019). "Therefore, the first assumption of why the mutated TRPM3 could induce epilepsy would be that mutated TRPM3 channels have increased basal activity." (PMID 33853504, 2021). "We propose that TRPM3 should be added in NGS panels designed for the diagnosis of epilepsy, ID, and congenital ataxia." (PMID 36648066, 2023). "Our findings suggest that TRPM3 is a locus for ID and epilepsy, and should be included in genetic panels targeting these indications." (PMID 31278393, 2019). "The data also raise the possibility that the direct inhibition of TRPM3 by primidone contributes to its antiepileptic effects, and that TRPM3 inhibitors may be developed to treat epilepsy in the future." (PMID 33853504, 2021). "Emerging evidence also connects TRPM3 dysfunction to neurodevelopmental disorders, particularly developmental and epileptic encephalopathies (DEE), which are characterized by epilepsy, intellectual disabilities, and musculoskeletal abnormalities." (PMID 40806522, 2025). "In this study, we present eight individuals with a neurodevelopmental phenotype comprising ID, hypotonia, epilepsy (seven individuals), and a recognizable craniofacial gestalt; exome sequencing showed de novo substitutions of a TRP (melastatin-related) channel, TRPM3, in each." (PMID 31278393, 2019).
developmental and epileptic encephalopathy (9 papers, 2020 to 2025). An epilepsy associated with developmental impairment that may be due to either the underlying etiology or the superimposed epileptic activity, or both. "In this study, we report an individual carrying a TRPM3 gene mutation with a clinical phenotype of developmental and epileptic encephalopathies (DEE)." (PMID 34074259, 2021). "The more surprising were two recent publications that reported de novo mutations in TRPM3 as the cause of developmental and epileptic encephalopathies (DEEs) in a total of nine patients." (PMID 33732703, 2021). "Several TRPM3 mutations are associated with brain dysfunction conditions such as intellectual disability and epilepsy as well as developmental and epileptic encephalopathy (DEE)." (PMID 39793986, 2025). "TRPM3 polymorphisms were reported to be associated with systemic sclerosis, aspirin-exacerbated respiratory disease (AERD), and developmental and epileptic encephalopathies (DEEs)." (PMID 35299963, 2022). "Further in-depth characterization has shown that two human disease variants in TRPM3 (V990/2M and P1090/2Q), which result in developmental and epileptic encephalopathy (DEE), can cause increased responses to PS, leading to elevated cytosolic calcium levels compared to wild-type TRPM3." (PMID 34948452, 2021).
glaucoma (8 papers, 2014 to 2024). Increased pressure in the eyeball due to obstruction of the outflow of aqueous humor. "Other interesting druggable targets were two transient receptor potential cation channels, encoded by TRPC1, found upregulated in glaucoma lamina cribrosa cells and TRPM3." (PMID 39458974, 2024). "Elevated IOP is a major risk factor for glaucoma in humans and the majority of family members segregating a cataract-causing mutation in TRPM3 also developed high-tension glaucoma." (PMID 32070426, 2020). "Here we map, identify, and characterize a mutation in TRPM3 associated with inherited cataract and glaucoma linked to human chromosome 9q." (PMID 25090642, 2014). "Mutation of TRPM3 has been identified in association with an ocular disease phenotype, in which a heterozygous mutation in TRPM3 segregated with disease in a large (five-generation) pedigree of congenital cataract and glaucoma." (PMID 30883612, 2019). "In addition to cataract and glaucoma, the TRPM3 mutation (I-to-M) discovered here was associated with a mild iris anomaly in three affected family members (V:3, V:4, V9), and in one case (V:9) anterior segment dysgenesis was also documented." (PMID 25090642, 2014). "Additionally, mutations in TRPM3 have been associated with inherited cataract and glaucoma." (PMID 38970055, 2024). "Additionally, TRPM3 mutations have been linked to inherited cataract and glaucoma." (PMID 38970055, 2024). "Recent genetic studies have discovered that mutation of the human TRPM3 gene underlies an inherited form of early-onset or pediatric cataract with or without glaucoma." (PMID 32070426, 2020). "In humans, mutation of TRPM3 underlies pediatric cataract with or without glaucoma and anterior segment defects, whereas mutation of MIR204 underlies retinal dystrophy and iris coloboma with or without cataract." (PMID 32070426, 2020). "By contrast, mutation of TRPM3 in humans underlies pediatric cataract (with or without glaucoma and anterior segment defects) suggesting a deleterious gain-of-function mechanism that may compromise lens Ca2+ homeostasis." (PMID 32070426, 2020). "The TRPM3 and TRPM5 channels are currently relevant to glaucoma research, with abundant expression of the Trpm3 gene observed in the ciliary body." (PMID 35185615, 2022). "TRPM3: Mutation of the gene for transient receptor potential (TRP) cation channel subfamily M (melastatin), member 3 (TRPM3) on chromosome 9q was first linked with autosomal dominant early onset, progressive cataract with or without glaucoma in an African American family." (PMID 38927721, 2024). "Notably, the ophthalmological findings reported in TRPM3-NDD include strabismus, nystagmus, and refractive errors but not cataracts, AMD, or glaucoma." (PMID 38334649, 2024).
glioma (7 papers, 2021 to 2024). A benign or malignant brain and spinal cord tumor that arises from glial cells (astrocytes, oligodendrocytes, ependymal cells). "TRPM3 has been identified in several cancer types in mammals, including kidney cell carcinoma, glioma, melanoma, and melanoma-associated retinopathy (MAR)." (PMID 37892239, 2023). "TRPM3 is widely distributed in the body, especially in the brain, and the dysregulation of its expression is closely related to glioma." (PMID 38680092, 2024). "MiR-204, located within the intron of the TRPM3 gene, is downregulated in glioma due to hypermethylation of the TRPM3 promoter." (PMID 39633507, 2024). "Bioinformatics analysis showed positive correlation between the host gene, TRPM3, and miR-204-3p in glioma patient tumor tissue." (PMID 36810326, 2023). "Both TRPM2 and TRPM3 have demonstrated protective roles in glioma; however, TRPM2 has been more thoroughly studied." (PMID 36768856, 2023). "A reduction in miR-204 induced by the higher methylation of host gene TRPM3 in gliomas can promote cell migration and enhance cell stemness." (PMID 37892239, 2023). "Four TRP melastatin subfamily members, TRPM2, TRPM3, TRPM7, and TRPM8, have been implicated in glioma cell growth, proliferation and migration." (PMID 33928077, 2021). "For instance, a study focusing on the role of miR-204 in high-grade glioma cell lines has revealed a significant down-regulation of TRPM3, due to the hypermethylation of its promoter." (PMID 33928077, 2021). "In conclusion, methylation of the TRPM3 is involved in the malignant phenotype of glioma." (PMID 38680092, 2024). "Still, there are few reports on the pathological function of TRPM3 in glioma." (PMID 38680092, 2024). "Specifically, TRPM2 and TRPM3 demonstrate anti-tumor effects in gliomas, while TRPM7 and TRPM8 may play a role in the malignant transformation of gliomas." (PMID 39633507, 2024). "Like TRPM2, TRPM3 may show a protective role in glioma probably via the miR-204 regulation, but its function needs further studies." (PMID 33928077, 2021). "TRPM3 may play a vital role as a tumor suppressor gene in glioma." (PMID 38680092, 2024). "Several TRP channels have been studied as potential biological markers of glioma progression and prognosis, including TRPC1, TRPC6, TRPM2, TRPM3, TRPM7, TRPM8, TRPV1/2." (PMID 36768856, 2023). "There is a growing consensus that TRPV1, TRPV2, TRPM2, TRPM3, and TRML1 exert anti-tumorigenic properties in glioma, while TRPC1, TRPC6, TRPM7, TRPM8, and TRPML2 promote glioma growth and proliferation." (PMID 36768856, 2023). "Furthermore, the downregulation of miR-204 via the methylation of the promoter of its host gene TRPM3 leads to the activation of the Src-STAT3-NFAT pathway, promoting glioma stem cell invasion and stem cell-like phenotype." (PMID 37892239, 2023). "Among them, TRPM2 and TRPM3 would exert anti-tumorigenic effects, while TRPM7 and TRPM8 may contribute to glioma malignancy." (PMID 33928077, 2021).